SOD1 (superoxide dismutase 1)
Diseases named in the same sentence as SOD1 in open-access papers (continued):
Sharing a sentence is not in itself a finding about the gene and the disease.
ovarian carcinoma (20 papers, 2006 to 2024). A malignant neoplasm originating from the surface ovarian epithelium. "We previously identified that overexpression of the antioxidant superoxide dismutase 1 (SOD1) in ovarian cancer is associated with a platinum-resistant phenotype via conferring oxidative stress resistance against platinum compounds." (PMID 37582934, 2023). "Kaplan–Meier curve analysis revealed a significant correlation (p < 0.05) between low expression of HSP90AA1, HSPA8, PSMA5, and SOD1 and prolonged overall survival (OS) in ovarian cancer patients." (PMID 38166541, 2024). "The study highlighted the potential therapeutic use of RNAi-mediated SOD1 targeting as a chemosensitizer for platinum-resistant ovarian cancers." (PMID 38068178, 2023). "In the quest for a novel therapeutic target for cisplatin resistance, we previously identified the ROS-neutralizing SOD1 to be overexpressed in cisplatin-resistant ovarian cancer cell lines using quantitative label-free comparative proteomics analysis." (PMID 37582934, 2023). "Our study highlights the potential therapeutic applicability of RNAi-mediated targeting of SOD1 as a chemosensitizer for platinum-resistant ovarian cancers." (PMID 37582934, 2023). "Their study investigated the potential of targeting SOD1 via RNA interference (RNAi) using PEGylated GO nanoparticles in platinum-resistant ovarian cancer." (PMID 38068178, 2023). "In cisplatin resistant human ovarian cancer cells, the SOD1 expression is higher than that in cisplatin-sensitive human ovarian cancer cells." (PMID 35978820, 2022). "The results indicated that Quercetin enhanced the endogenous antioxidant enzyme SOD1 expression of ovarian cancer cells in vivo, and prevented ROS-induced damage." (PMID 24999622, 2014). "SOD1 is a critical determinant of platinum resistance in ovarian cancer and represents a target for overcoming this resistance.Small nucleolar RNAs (snoRNAs) are noncoding RNAs that form ribonucleoproteins involved in guiding covalent modifications of ribosomal and small nuclear RNAs in the nucleus." (PMID 38166541, 2024). "The expression of SOD1 is direct to increased median survival of patients with ovarian cancer." (PMID 37968795, 2024). "Thus, our previous results suggest the role of SOD1 overexpression as a defense mechanism of ovarian cancer cells to counteract platinum-induced oxidative stress and modulation of ROS-mediated redox signalling." (PMID 37582934, 2023). "Previous studies demonstrate that TETA could overcome cisplatin resistance in human ovarian cancer cell cultures, via inhibition of Cu/Zn superoxide dismutase, namely, SOD1." (PMID 28280522, 2017). "This approach might, in particular, be applied to treat MDR tumors because, for example, SOD1 is a therapeutic target of TM and inhibition of SOD1 was shown to restore the cisplatin-sensitivity in resistant ovarian cancer cells." (PMID 22502731, 2012). "Some studies further demonstrated a significantly increased expression of CuZnSOD (SOD1), MnSOD (SOD2), and catalase in chronic lymphocytic leukemia cells and ovarian cancer cells." (PMID 23431283, 2013). "Positive expression of SOD1 was primarily a cytoplasm pattern in ovarian cancer cells rather than stromal cells." (PMID 24999622, 2014).
Zinc deficiency (20 papers, 2009 to 2025). A deficiency of the essential metal Zinc; an essential cofactor for many enzymes. "In S. pombe, as well as in other organisms such as S. cerevisiae, Arabidopsis, and Sorghum, Sod1 protein levels are reduced in response to zinc deficiency." (PMID 39761853, 2025). "Given that zinc deficiency causes increased oxidative stress, and Sod1 has a well-established role as an antioxidant, why would cells lower the levels of Sod1 under low zinc conditions?" (PMID 39761853, 2025). "An alternative explanation for the zinc-dependent changes in sod1 mRNA levels is that zinc deficiency affects the activity of one or more of these enzymes, which in turn alters the composition of the tRNA pool." (PMID 39761853, 2025). "Here we show that sod1 mRNA and protein levels are reduced in response to zinc deficiency and that this regulation occurs in a manner that is dependent on the Caf1 and Ccr4 deadenylases of the CCR4-NOT complex." (PMID 39761853, 2025). "Zinc deficiency impairs the catalytic function of numerous antioxidant enzymes, notably copper/zinc superoxide dismutase (SOD1), compromising its critical role in preventing oxidative DNA damages." (PMID 40463468, 2025). "Zn serves as a cofactor for the antioxidant enzyme Cu, Zn-superoxide dismutase (SOD1), and its activity is attenuated in conditions of zinc deficiency." (PMID 38999951, 2024). "Our findings showed that zinc deficiency can inhibit the NRF2-HO1/SOD1/2 signaling pathway, indicating that zinc acted as an essential anti-oxidative element in the ovaries, maintaining the redox homeostasis." (PMID 38807213, 2024). "Consistently, our results showed that zinc deficiency greatly reduced the protein expression of HO-1 and SOD1/2 in the ovaries." (PMID 38807213, 2024). "Taken together, our observations indicated that zinc deficiency induces oxidative stress in the ovaries by inhibiting the NRF2-HO1/SOD1/2 signaling pathway." (PMID 38807213, 2024). "It is important to mention that zinc supplementation protects ALS mutant G93A SOD-1 transgenic mice against the toxicity of ALS-associated SOD, which suggests that toxicity is connected with zinc deficiency in G93A SOD-1." (PMID 35630637, 2022). "SOD1 mutants appear to gain a toxic property or function, rather than losing O2− scavenging activity, and wild-type SOD1 can become toxic through oxidative post-translation modification and zinc deficiency." (PMID 33381076, 2020). "Oxidative stress associated with long term zinc deficiencies can be attributed to a reduction in the synthesis of MTs and a decline in the antioxidant activity of zinc-containing Cu, Zn superoxide dismutase (SOD1)." (PMID 29295546, 2017). "Dietary zinc deficiency has been shown to induce hepatic lipid peroxidation in association with reduction of antioxidant enzymes such as SOD-1." (PMID 24155903, 2013). "Up-regulation of p47phox and down-regulation of SOD-1 proteins were the major synergistic effects of zinc deficiency and ethanol on hepatic pro-oxidant and antioxidant systems." (PMID 24155903, 2013). "Because of this fact, one of the proposed mechanisms for the source of oxidative stress under zinc deficiency is loss of Sod1 activity and the consequent build up of ROS that is constitutively generated by aerobic metabolism." (PMID 19756144, 2009). "While this could potentially lead to elevated levels of unfolded Sod1 protein, yeast upregulate protein chaperones during zinc deficiency to mitigate the increased burden of unfolded proteins." (PMID 39761853, 2025). "The regulation of Sod1 protein levels by zinc may play a protective role for cells under both zinc deficiency and excess conditions." (PMID 39761853, 2025). "Therefore, we compared the protein levels of HO-1 and SOD1/2 in the control and zinc deficiency groups." (PMID 38807213, 2024). "This implied that zinc deficiency affected the protein level of NRF2-HO1/SOD1/2 signaling pathway." (PMID 38807213, 2024).
Zinc deficiency (continued). "Zinc deficiency or mutations in SOD1 resulting in a zinc deficient enzyme may disrupt SOD1’s function creating a shift to prooxidant activity." (PMID 37996893, 2023). "To investigate this hypothesis, we first examined the effects of zinc deficiency on SOD1 expression, protein accumulation, and SOD activity." (PMID 19756144, 2009). "To investigate the functional role of Sod1 in zinc-limited cells, we examined whether Sod1 activity was required to combat the oxidative stress of zinc deficiency." (PMID 19756144, 2009). "Zinc deficiency induced the expression of certain zinc transporters (ZIP14, ZIP10, ZIP6, ZIP4, ZnT4, ZnT9) as well as of SOD1, IGF I and IGF II, while expression of ZnT1 and metallothionein (MT) was reduced." (PMID 36979030, 2023). "We also found that zinc deficiency caused a conformational change of SOD1WT to a mutant-like form (exposure of the DBR), resulting in SOD1-Derlin-1 interaction." (PMID 29991716, 2018). "Synergistic effects of dietary zinc deficiency on ethanol-induced oxidative stress in the liver were associated with an increased imbalance between pro-oxidative and antioxidant enzymes, particularly, the increase of NADPH oxidase and decrease of SOD-1." (PMID 24155903, 2013). "Interestingly, we observed a significant reduction in the mRNA levels of Ho-1 and Sod1 in the zinc deficiency group, while there were no changes in the Nrf2 expression." (PMID 38807213, 2024).
cognitive decline (19 papers, 2014 to 2025). "The median SOD1 levels were significantly increased in the platelets of AD patients by 8% (p = 0.036) and, importantly, showed an early peripheral change during cognitive decline with a 9% (p = 0.003) rise in MCI patients versus controls." (PMID 40189792, 2025). "Although increased SOD has been reported in the brain and blood, this is the first study linking alterations in SOD1 and CCS in platelets to early cognitive decline in AD." (PMID 40189792, 2025). "No sensory symptoms or cognitive decline are noted in the SOD1-JALS cases." (PMID 34946884, 2021). "Behavioural measures reveal higher levels of apathy in SOD1 FALS patients compared to controls, although this is attributed more to the physical limitations of the disease rather than cognitive decline." (PMID 40649976, 2025).
hypothyroidism (18 papers, 2005 to 2025). Abnormally low levels of thyroid hormone. "The genes Sod1, Sod2 and Gpx1 were reduced in tests on rats with hypothyroidism, which is similar to previous studies conducted on this species." (PMID 38338793, 2024). "Although Kp10 did not change the low expression of these genes caused by hypothyroidism, a significant increase in the immunostaining of SOD1 and GPX1/2 was observed after treatment, highlighting their antioxidant effects in tests on hypothyroid rats." (PMID 38338793, 2024). "Hypothyroidism increased apoptosis index, TBARS and LOOH concentrations, and reduced testicular gene expression of Sod1, Sod2 and Gpx1, as well as the expression of Grp78, Atf6, Ho1 and Chop." (PMID 38338793, 2024). "Treatment with Kp10, in turn, reduced testicular apoptosis and the production of peroxynitrite, while increased SOD1 and GPX 1⁄2 expression, and enzymatic activity of CAT, but did not affect the lower expression of UPR mediators caused by hypothyroidism." (PMID 38338793, 2024).
osteoarthritis (18 papers, 2018 to 2025). A noninflammatory degenerative joint disease occurring chiefly in older persons, characterized by degeneration of the articular cartilage, hypertrophy of bone at the margins and changes in the synovial membrane. "SOD1 has been shown to become less abundant in the aged IVD and in osteoarthritis." (PMID 33382035, 2020). "The role of SIRT4 in RA has not been studied, but SIRT4 can affect osteoarthritis through a variety of inflammatory factors, such as TNFα and IL-6, and the effect of SIRT4 on oxidative stress has also been proven the increased expression of SIRT4 can up-regulate SOD1, SOD2, and catalase." (PMID 37238636, 2023).
preeclampsia (18 papers, 2009 to 2025). Preeclampsia is a hypertensive disorder of pregnancy that is characterized by new-onset hypertension with proteinuria presenting after 20 weeks of gestation, and depending on mild or severe forms may initially present with severe headache, visual disturbances, and hyperreflexia. "Molecular docking analysis showed that HK2, SH3BP5, and SOD1 exhibited significant binding affinities with two preeclampsia drugs." (PMID 40966654, 2025). "Further analysis of gene regulatory networks, including transcription factor–gene, gene–microRNA, and drug–gene interactions, revealed that seven hub genes (HK2, SRSF10, SOD1, ERO1L, IRF3, MME, and SH3BP5) were strongly associated with preeclampsia." (PMID 40966654, 2025). "In the placenta of patients with preeclampsia, SOD1 gene was found to be abnormally methylated, and its expression was significantly decreased." (PMID 41472113, 2025). "Constructed a protein–protein interaction (PPI) network, identifying 10 hub genes, seven of which (HK2, SRSF10, SOD1, ERO1L, IRF3, MME, and SH3BP5) were strongly linked to preeclampsia." (PMID 40966654, 2025). "Previous work has reported reduced SOD1 mRNA and SOD activity in isolated trophoblasts from preeclampsia patients." (PMID 27604418, 2016). "Incubation with preeclampsia plasma induced a significant increase in SOD1 gene expression (1.32 ± 0.10 fold, n = 8, P < 0.05), SOD2 gene expression (1.35 ± 0.21 fold, n = 8, P < 0.05) and HO-1 gene expression (1.82 ± 0.42 fold, n = 8, P < 0.05) respectively compared to uncomplicated pregnancy." (PMID 27604418, 2016). "These compensatory changes, along with the increase in SOD1 and SOD2 reported herein, may impart a protective effect on the placenta and the developing fetus in response to additional stressors, such as maternal obesity or preeclampsia." (PMID 32628362, 2020).
pulmonary hypertension (18 papers, 2012 to 2025). Increased pressure within the pulmonary circulation due to lung or heart disorder. "Increased EZH2 activity inhibits SOD1 expression leading to ROS accumulation that contributes to the progression of pulmonary artery hypertension." (PMID 38580969, 2024). "Furthermore, fawn-hooded rats, which have an epigenetic silencing of SOD2 expression/activity, and SOD1 knockout mice develop spontaneous pulmonary hypertension." (PMID 28666030, 2017). "For example, SOD1 and SOD3 expression and activity are decreased in chronic hypoxia-induced pulmonary hypertensive mice, rats, calves, and piglets and in a lamb model of persistent pulmonary hypertension of the newborn." (PMID 28666030, 2017). "Accumulating evidence has suggested that impaired activity of SOD2 and SOD3 contributed to pulmonary hypertension, and the level and activity of SOD1 has not been found significantly changed in human pulmonary hypertension." (PMID 33947399, 2021).
sporadic amyotrophic lateral sclerosis (18 papers, 2011 to 2026). Sporadic amyotrophic lateral sclerosis is a amyotrophic lateral sclerosis in which there is no known cause, such as no family history. "In relation to the comparator groups SOD1 (n = 20) and sporadic amyotrophic lateral sclerosis (n = 753), C9orf72 patients generally obtained the worst results in all domains with the exception of spatial perception which was normal in all three groups." (PMID 37006326, 2023). "We already demonstrated that in peripheral blood mononuclear cells (PBMCs) of sporadic amyotrophic lateral sclerosis (sALS) patients, superoxide dismutase 1 (SOD1) was present in an aggregated form in the cytoplasmic compartment." (PMID 31121901, 2019). "Expression levels of miR-155 are increased in the spinal cord of both familial and sporadic amyotrophic lateral sclerosis and genetic ablation of miR-155 markedly increased survival in SOD1 mice with restoration of abnormal microglia." (PMID 26376862, 2015). "Several lines of evidence support the hypothesis of a toxic role played by wild type SOD1 (WT-SOD1) in the pathogenesis of sporadic amyotrophic lateral sclerosis (SALS)." (PMID 24155874, 2013). "Activation of the UPR is observed in mutant superoxide dismutase-1 transgenic mice, and increased levels of ER stress markers, as well as wild-type superoxide dismutase-1 aggregates have been reported in spinal cord tissue of sporadic amyotrophic lateral sclerosis." (PMID 21808733, 2011).
Cirrhosis (17 papers, 2008 to 2025). A chronic disorder of the liver in which liver tissue becomes scarred and is partially replaced by regenerative nodules and fibrotic tissue resulting in loss of liver function. "In contrast, measurement of hepatic SOD1 gene expression showed that the mRNA level of liver SOD1 was significantly decreased in subjects with cirrhosis secondary to MASH as compared to subjects with cirrhosis secondary to primary biliary cirrhosis as well as with healthy controls, respectively." (PMID 39443317, 2025).
fungal infection (17 papers, 2012 to 2025). "Our findings revealed that fungal infection interrupted the antioxidant defense system by increasing the level of the oxygenase COX2 and reducing the level of the antioxidant enzyme SOD1, which caused oxidative stress in inflamed corneal tissue." (PMID 28874754, 2017). "Data for the involvement of superoxide dismutases in fungal infection of plants is based primarily on correlations with SOD gene transcription during fungus-plant interaction, but genetic evidence of the role of superoxide dismutase is largely lacking or contradictory in the case of Botrytis Sod1." (PMID 22615571, 2012). "Fungal infections also increase HMOX1 and COX2 expressions and inhibit the levels of antioxidant enzymes, superoxide dismutase-1 (SOD1), glutathione peroxidase-1 (GPx1), and peroxide resin-4 (PRDX4)." (PMID 39763659, 2024). "Fungal infection also increased the mRNA expression and protein production of heme oxygenase-1 (HMOX1) and cyclooxygenase-2 (COX2), with suppressed levels of antioxidant enzymes, superoxide dismutase-1 (SOD1), glutathione peroxidase-1 (GPx1) and peroxiredoxin-4 (PRDX4)." (PMID 28874754, 2017).
liver disease (17 papers, 2008 to 2025). "Using DKO mice in which both Sod1 and Prdx4 were deleted, we show that oxidative stress in association with ER stress leads to the development of a very severe hepatic disorder." (PMID 30050648, 2018).
male infertility (17 papers, 2012 to 2026). The inability of the male to effect fertilization of an ovum after a specified period of unprotected intercourse. "A recent systematic review demonstrated that many sperm proteins associated with male infertility—particularly those involved in oxidative stress regulation and mitochondrial function (e.g., PRDX6, SOD1, AKAP4)—are not detected by routine semen analysis." (PMID 41011106, 2025).
pancreatic cancer (17 papers, 2016 to 2025). "Exogenous murine REG2 protein inhibited the proliferation of Gpx1-/- and Sod1-/- islets and decreased cell viability of human pancreatic cancer cells (PANC1)." (PMID 37107224, 2023). "Although SOD1 is highly expressed and act as oncogene in many cancers but in pancreatic cancer cells SOD1 has differentially expressed." (PMID 36809279, 2023). "Study show the SOD1 could accelerate the invasive and migratory of pancreatic cancer by the H2O2/ERK/NF-κB axis and regulate the expression of EMT-related genes." (PMID 37223030, 2023). "However, in pancreatic cancer cells, these effects were more severe, and it was shown that they could diminish superoxide dismutase 1 (SOD1) expression by transferring miR-6823-5p." (PMID 39796230, 2025). "Although SOD1 shows highly expressed in many cancers and functions as an oncogene, it is still need to be furtherly studied whether SOD1 acts as the similar role in pancreatic cancer." (PMID 32391354, 2020). "Among the up-regulated is the superoxide dismutase 1 Sod1, described to promote the epithelial-mesenchymal transition (EMT) of pancreatic cancer cells via activation of the H2O2/ERK/NF-κB axis and to be involved in aging." (PMID 32842712, 2020). "SOD2 expression is higher than SOD1, SOD3, and CAT in pancreatic cancers." (PMID 37891871, 2023). "Moreover, we detected AgNP-induced disturbance of antioxidant system (SOD1, SOD2, GPX-4, CAT, and SOD3) in pancreatic cancer cells." (PMID 30186549, 2018).